PLG (plasminogen)
Diseases named in the same sentence as PLG in open-access papers (continued):
Sharing a sentence is not in itself a finding about the gene and the disease.
cancer (continued). "The importance of plasmin to the modulation of dendritic cell function should now be assessed in disease settings such as burns and cancer – instances where immunosuppression and substantial binding of t-PA/plasminogen to necrotic tissue are commonplace." (PMID 26132730, 2015). "Our studies stress, however, that these cells in particular seem to play a central role for cancer invasion through the plasminogen activation system in urothelial neoplasia of the bladder, and these results can be directly translated into survival." (PMID 26292086, 2015). "It is also expressed on the cancer cell surface, acting as a plasminogen activator that leads to activate plasminogen into plasmin." (PMID 25788858, 2014). "The plasmin is generated from plasminogen in the vicinity of the cancer cells by the action of urokinase plasminogen activator (uPA) which is often localized in the invading front via its receptor (uPAR)." (PMID 25180193, 2014). "In this review, we will highlight the importance of the best-characterized components of the PLG/PLA cascade in the pathogenesis of cancer focusing on the role of the cell surface-PLG receptors (PLG-R)." (PMID 25407528, 2014). "In fact, when up-regulated, ANX2 contributes to cancer invasion and metastasis by acting as a co-receptor for plasminogen, tPA and pro-cathepsin B." (PMID 23594883, 2013). "An earlier study proposed that binding of the ligand to urinary-type plasminogen activator receptor: uPAR promotes cancer cell invasion by activation of plasminogen, leading to the degradation of extracellular matrix." (PMID 22898004, 2012). "It has also been established that plasminogen activator inhibitor-1 (PAI-1), urokinase plasminogen activator (uPA) and uPA receptor (uPAR), members of the plasminogen activation system (PA system), play a key role in cancer invasion and metastasis." (PMID 19055748, 2008). "Tumour progression seems to be dependent on cancer cell controlled tissue remodelling, including angiogenesis, mediated to a large extent by the plasminogen activation system." (PMID 12556967, 2003). "Angiogenesis and extracellular proteolysis of the plasminogen activation system are of crucial importance in cancer metastasis." (PMID 12556967, 2003). "In conclusion, these results shed further light on the functional organisation of the plasminogen activation cascade on the surface of a metastatic cancer cell." (PMID 11556845, 2001). "Both methods have been used to investigate the impact of the plasminogen activation (PA) system in cancer." (PMID 10188903, 1999). "Plasminogen activator zymographs of the conditioned media from the cancer cells showed that CSF treatment resulted in an increase in a 48–55 kDa plasminogen-dependent gelatinolytic activity that was characterized as human uPA." (PMID 10408691, 1999). "The crucial role of non-plasminogen dependent serine proteinases is tissue invasive and cytolytic functions of Walker 256 cancer cells has been documented using a rat urinary bladder invasion and a 125I-labelled fibroblast cytolysis assay." (PMID 2992566, 1985). "PLG participates in fibrinolysis, and C8B helps in the clearance of cancer cells." (PMID 41271007, 2025). "However, serpins that inhibit plasminogen activators produced by cancer cells, including neuroserpin and serpin B2, prevent the generation of plasmin." (PMID 40076927, 2025). "Notably, compared to paired normal tissues, lower PLG expression was observed in eight cancer types, with the exception of LUSC, which showed high expression of PLG." (PMID 39179711, 2024). "A systematic study of the progression of missense somatic mutations of PLG and their potential role in cancer evolution is lacking." (PMID 38984351, 2024). "Activation of plasminogen could promote cancer cell proliferation; thus, inhibition of this pathway by SLURP1 could have huge implications on cancer inhibition." (PMID 37896222, 2023).
cancer (continued). "S100A10 is involved in various cellular processes, regulates plasminogen activation and has been shown to suppress pro-apoptotic capacity of Bcl-2-associated death protein (BAD), which is suggested to have anti-apoptotic function in cancer cells." (PMID 36230614, 2022). "Cancer cell migration/invasion can be affected by components of the plasminogen-plasmin system." (PMID 36119528, 2022). "uPA is a highly restricted serine protease that converts the zymogen plasminogen to active plasmin, a broad-spectrum serine proteinase capable of degrading most protein components of the extracellular matrix, facilitating cancer invasion and metastasis (one of the cancer hallmarks)." (PMID 35327524, 2022). "uPAR has been shown to be upregulated in cancer cells, to play a critical role in driving plasminogen-dependent matrix degradation and to affect a variety of physiological and pathological processes, including cell migration, invasion, adhesion, survival and proliferation." (PMID 36703790, 2022). "The researchers also postulate that E. faecalis promotes the migration of cancer cells through its ability to activate the pro-uPA component of the urokinase–plasminogen system, a pathway that is well-known to be important in the invasion and migration of cancer cells." (PMID 35745541, 2022). "Given that sENO1 is known to promote cell invasion through activating the uPA/uPAR/plasminogen axis, we posited that sENO1+ cells may comprise the pro-invasive subset of cancer cells." (PMID 34136381, 2021). "Interestingly, the plasminogen/plasmin effects on autophagy in cancer cells seem to depend on the cancer cell type." (PMID 33669052, 2021). "In breast cancer, researchers have established a mathematical model of cancer recurrence focusing on monitoring of tissue biomarkers, including markers in the plasminogen system, and found that only the serum concentration of uPAR in cancer patients was positively correlated with cancer recurrence." (PMID 34729105, 2021). "Multiple lines of evidence reveal that ENO1 is also present on the plasma membrane of cancer cells in non-small cell lung, breast, and pancreatic cancers, where it activates the plasminogen activator receptor (uPAR)/plasminogen/MMP axis, resulting in collagen degradation and cell invasion." (PMID 34136381, 2021). "At the cell surface, AnxA2 heterotetramer complex provides binding site for both plasminogen and tissue type plasminogen activator (tPA) and converts plasminogen into plasmin, which plays an important role in invasion and metastasis of cancer." (PMID 33374917, 2020). "No significant degradation was observed with cancer-associated fibroblasts after 30 min, even in the presence of plasminogen." (PMID 33425767, 2020). "However, PLG is not only a pro-tumorigenic factor but also an anti-tumorigenic factor due to the fact that proteolysis of PLG can release angiotensin, which will function against cancer progression." (PMID 32002016, 2020). "Potentially, SAA could promote cancer progression by inhibiting platelet adhesion and enhancing plasminogen activation, both of which were involved in extracellular matrix (ECM) degradation and tissue remodeling." (PMID 31907639, 2020). "MMP-7 and MMP-9 may be involved in the blockage of cancer angiogenesis by cleaving plasminogen and generating angiostatin molecules." (PMID 31921634, 2019). "Furthermore, blockade of PLG with monoclonal antibodies, DNA-based vaccination or silencing through small interfering RNAs has been recently proposed to counteract cancer invasion and metastasis." (PMID 29713020, 2018). "The plasminogen activation system is involved in cancer cell invasion and metastasis." (PMID 30518748, 2018). "Subsequent assessment of cancer cell invasion revealed that S100A10 depletion reduced the ability of Panc‐1 cells (by 64%) to pass through the ECM‐dense matrigel even in the presence of exogenous plasminogen (+Pg) compared to scramble control cells." (PMID 30009399, 2018).
cancer (continued). "This suggests that the inhibition of plasminogen/plasmin might be a novel treatment for preventing radiodermatitis in cancer therapy." (PMID 30323258, 2018). "PLG is activated by the urokinase-type PLG activator which is produced by cancer or stroma cells." (PMID 28491013, 2017). "In this review we will focus on the multifunctional role of the PLG/PLA system in the pathogenesis of human cancer and, in particular, we will discuss the mechanisms involved in the regulation of PLG-R trafficking and highlight novel/potential anticancer therapies targeting these molecules." (PMID 25407528, 2014). "Moreover, most plasminogen system components are cell surface-expressed and therefore represent readily accessible targets for cancer therapy." (PMID 23594883, 2013). "Several components of the plasminogen activation system, including PA1-1, are implicated in tissue remodeling associated with both physiological and pathologic processes such as wound healing, mammary gland involution, angiogenesis, and cancer invasion." (PMID 21303533, 2011). "By binding to plasminogen, tetranectin may enhance activation of plasminogen to plasmin, which plays a role in the degradation of extracellular proteins and cancer progression." (PMID 20957082, 2010). "Likewise, the urokinase-type (uPA) plasminogen activator system has been shown to play a crucial role in cancer metastasis." (PMID 12556967, 2003). "The uPA-mediated pathway of plasminogen activation is central to cancer metastasis." (PMID 9528837, 1998). "To date, no PLG germline genetic variants have been reported to directly lead to cancer." (PMID 38984351, 2024). "However, a potential role of PLG missense somatic variants in cancer (and other diseases) should not be ruled out." (PMID 38984351, 2024). "The heterotetramer could activate the plasminogen activation pathway, playing a key role in cellular repair and further promoting degradation of the extracellular matrix to increase the invasion capability of carcinoma cells." (PMID 39290334, 2022). "Cancer cells surviving therapy as residual disease (RD) expressed an alveolar-regenerative cell signature suggesting a therapy-induced primitive cell-state transition, whereas those present at on-therapy progressive disease (PD) upregulated kynurenine, plasminogen, and gap-junction pathways." (PMID 32822576, 2020). "Moreover, plasminogen can bind to several cell surface proteins forming a complex, which plays a crucial role in both physiologic and pathologic processes such as inflammation, thrombosis, and cancer." (PMID 31355216, 2019). "uPA binds with high affinity to uPAR and, consequently, converts plasminogen to active plasmin, which activates several proteases related to the degradation of extracellular matrix proteins and basal membranes, thereby facilitating cancer cell invasion and metastasis." (PMID 27933281, 2016). "The interaction of PLG and TPA produces plasmin that promote fibrinolysis, an important process in cancer progression." (PMID 40396123, 2025). "Our analysis identified that C1S, F3, and PLAT as genes with notably high expression, while PLG, SERPINC1, and F2 exhibited lower expression levels across most cancers." (PMID 39179711, 2024). "suPAR is believed to facilitate the spread of cancer cells through various mechanisms, including degrading and dissolving extracellular matrix (ECM) by activating the plasminogen activation system and promoting chemotaxis." (PMID 37875832, 2023). "PLG regulates macrophage invasion, MMP proteins, or CCL2/CCR2 axis and is involved in cancer cell proliferation, migration, growth, and metastasis." (PMID 34861103, 2022). "uPA is activated by binding to uPA receptors (uPAR) and converts the inactive enzyme plasminogen into the active serine protease plasmin, which engages in the degradation of extracellular matrix (ECM) and promotes cancer invasion and metastasis." (PMID 36195918, 2022).
cancer (continued). "The expression of the components of the plasminogen activation system by malignant cells and the surrounding stromal cells modulates the TME resulting in sustained cancer progression signals." (PMID 33921488, 2021). "S100A10 and uPAR co-localize at the cell surface bringing together plasminogen and uPA and therefore promoting the generation of the serine protease, plasmin and subsequent degradation of the ECM which is fundamental for cancer cell invasion." (PMID 32867190, 2020). "The active form of the serine protease uPA converts plasminogen into plasmin, which in turn degrades the ECM directly or through the activation of pro-matrix metalloproteinases, thus promoting cancer cell metastasis and invasion." (PMID 30428522, 2018). "MMP-9 is part of the MMPs family and is the most important component in cancer tissue remodeling, able to catalyze types V, VII, IX, X, and IV collagen, elastin, fibrin, fibrinogen and plasminogen to facilitate malignant cell invasion and metastasis." (PMID 26918342, 2016). "In cancer progression, two major classes of proteases play a crucial role, the matrix metalloproteinase (MMP) family and the plasminogen activation system." (PMID 25668817, 2015). "Urokinase (uPA) and tissue (tPA) plasminogen activators released from cancer cells catalyze the proteolytic conversion of plasminogen to plasmin, leading to degradation of the extracellular matrix (ECM), thus facilitating cancer cell invasion." (PMID 25860938, 2015). "Urokinase-type plasminogen activator receptor has been shown to be up-regulated in cancer cells and to play a critical role to regulate the cells-ECM interactions, promoting its degradation and turnover through the plasminogen activation cascade 31,45." (PMID 25215932, 2014). "When present on the cancer cell surface, CK8 binds plasminogen and promotes its activation through plasminogen activators." (PMID 23594883, 2013). "The plasminogen activation system, including PAI-1 (plasminogen activator inhibitor 1), plays a crucial role in the process of cancer." (PMID 17118139, 2006). "In order to facilitate tissue remodeling, cell migration, and cancer invasion, UPA, a serine protease, transforms plasminogen into plasmin, which is a protease that breaks down fibrin and other ECM components and promotes the activation of additional matrix-degrading enzymes." (PMID 40362600, 2025). "The plasminogen system and the Matrix Metallo-Proteases (MMPs), in particular MMP-2 and MMP-9, constitute two main systems involved in extra-cellular matrix (ECM) degradation, invasion and metastasis in many cancers." (PMID 32867190, 2020). "Urokinase plasminogen activator converses the inactive zymogen plasminogen by proteolytic cleavage to activate the serine proteinase plasmin, which in turn catalyzes the degradation of ECM, thereby facilitating the invasion of cancer cells." (PMID 23940799, 2013). "However, eHsp90 is primarily known for enhancing the invasiveness of cancer cells by interacting with ECM proteins and ECM-modifying proteins present in the TME, such as Matrix Metalloproteinase (MMP)-2, MMP9, Plasminogen, Collagen-1, Fibronectin (FN), and LOX-like protein-2 (LOXL2)." (PMID 39594828, 2024). "As mentioned in the previous Section 2.1, most of metastatic cancer cells may not survive due to the action of astrocytes by generation of plasmin from neuron-derived plasminogen, which promotes release of membrane-bound astrocytic FasL." (PMID 29641478, 2018). "When CM was analyzed by gelatin and plasminogen zymography, reduced levels of 72/92 kDa (MMP2/MMP9) and 70/45kDa (tPA/uPA) zone clearing activity were detected from daurinol treated MDA-MB-231 and A549 cancer cells compared to the control in a concentration-dependent manner." (PMID 28915654, 2017).
cancer (continued). "Cell surface expression of alpha-enolase, a glycolytic enzyme displaying moonlighting activities, has been shown to contribute to the motility and invasiveness of cancer cells through the protein non-enzymatic function of binding plasminogen and enhancing plasmin formation." (PMID 28630480, 2017). "Considering the specificity of plasminogen-derived p22 for endothelial cells, we expected that if the p22 component of the DT385-p22 fusion protein, then DT385-p22 should only target endothelial cells and not cancer cells, as has been demonstrated for plasminogen-derived p22." (PMID 20463924, 2010). "Similarly, HSP70 was shown to assist in surface membrane translocation of alpha-enolase, an enzyme shown to contribute to the motility and invasiveness of cancer cells through the protein non-enzymatic function of binding plasminogen and enhancing plasmin formation." (PMID 34943954, 2021). "The components of the plasminogen activation system (PAS) are important determinants of metastatic capacity, participating in both proteolytic and non-proteolytic pathways during cancer progression." (PMID 17257442, 2007). "However, no studies have directly evaluated the contribution of plasminogen itself to PDAC and analyses of the potential contribution of plasmin(ogen) to tumor growth of other cancer types is limited." (PMID 37971174, 2024). "The urokinase (uPA)-mediated plasminogen activation system (PAS) includes uPA, its inhibitors PAI-1 and PAI-2 and its specific cellular receptor uPAR; their increased expression represents a negative prognostic factor in several cancers." (PMID 36674481, 2023). "Suppression of CDCP1 cleavage by TA may be preferable to that induced by TGFβ and glucocorticoids since these agents block Plasminogen activation by upregulating Plasminogen Activator Inhibitor-1 (PAI-1) and activate transcriptional programs that may not be beneficial in the cancer setting." (PMID 35095503, 2021).